ABCB1 (ATP binding cassette subfamily B member 1)
Diseases named in the same sentence as ABCB1 in open-access papers (continued):
Sharing a sentence is not in itself a finding about the gene and the disease.
tumor (continued). "We established an ABCB1 overexpressing tumor xenograft mouse model to investigate whether TNP can effectively deliver DOX into tumors and bypass the efflux function of the ABCB1 transporter, thereby increasing the intratumoral accumulation of DOX and potentiating the anticancer activity of DOX." (PMID 26716507, 2016). "An important observation from the work by Traxl and colleagues, which may have important clinical significance for the use of [11C]erlotinib, is the fact that the distribution of [11C]erlotinib in peripheral, and probably tumor tissues, was affected by ABCB1/ABCG2." (PMID 26690113, 2015). "Moreover, both immunohistochemical and immunofluorescent assays showed that afatinib could also attenuate the expression of ABCB1 protein in tumor tissues in vivo." (PMID 26317651, 2015). "Because of the important role of Pgp in drug disposition, it seems as a fair presumption that such SNPs could have clinical importance in drug pharmacokinetics and, by extension, in pharmacodynamics (and even direct impact on PD in tumor cells with overexpression of MDR1/ABCB1)." (PMID 23766564, 2013). "The mammalian multidrug transporter ABCB1 (also termed P-glycoprotein or MDR1) has probably attracted most attention of all ABC transporters, since it can play an important role in the extrusion of noxious substances out of the cell, and has been linked to drug resistance in tumor cells." (PMID 22675494, 2012). "Nonetheless, the pharmacokinetic signals observed, together with emerging technologies capable of selectively modulating efflux activity at the tumour-BBB interface, point to a continued role for ABCB1 in future therapeutic strategies." (PMID 41957561, 2026). "Many phytochemicals also sensitize CSCs to chemotherapeutic agents by downregulating drug-efflux transporters (e.g., ABCB1, ABCG2) and lowering survival thresholds, resulting in enhanced apoptosis and reduced tumor-initiating potential." (PMID 41595749, 2026). "Protein-protein interaction analysis identified four hub genes-ASPN, SELE, ACKR1 and ABCB1-integrating ECM remodelling, endothelial-immune modulation and xenobiotic transport, reinforcing an immune-attenuated, metabolically adapted tumour landscape." (PMID 42194092, 2026). "In vivo, OF12-GEL significantly suppressed tumor growth in both DMBA-induced SCC rats and A431 xenograft mice, reducing tumor volume by and improving survival to 60%, and markedly downregulating BCL-2, Ki67, TNF-α, and ABCB1." (PMID 41705136, 2026). "This is not only because of the impact of ABCB1/ABCG2 activity in the BBB, but also because of ABC transporter-mediated multidrug resistance potentially occurring in tumor cells themselves." (PMID 40893689, 2025). "In some cases it has been shown that the expression of ABCB1 and ABCG2 can also increase over time in these tumor cells." (PMID 40893689, 2025). "ABCB1 (P-glycoprotein), a well-characterized ABC transporter that is known to efflux chemotherapeutic agents from tumor cells, is upregulated by the lncRNA SBF2-AS1, promoting TMZ resistance." (PMID 40896358, 2025). "For TMZ specifically, the inhibition of ABCB1, ABCG2, ABCE1, ABCC1, and ABCB5 has seen significant decreases in either GBM tumor volume/weight by (~40–90% reduction), or significant increases in median survival (~1.3- to 5-fold increase)." (PMID 39861164, 2025). "Hyper‐expression of ABCB1, ABCG2, or ABCC1 has been documented in clinical tumor specimens to mediate MDR and poor prognosis in patients bearing malignancies in breast, liver, blood, colon, and lung." (PMID 41328326, 2025). "The tumor tissues produced from the OVCAR3-shCYLD group had higher expression levels of Bcl-XL and ABCB1, but lower expression levels of Bax." (PMID 40012003, 2025). "The viability of tumor specimens was analyzed by MTT assay and an Image Analysis System, and the expression of ABCB1, ABCG2, and ABCC1 proteins in specimens was synchronously detected via western blot assays." (PMID 41328326, 2025).
tumor (continued). "To explore melatonin′s mitochondrial effects on CDDP resistance in vivo, we examined tumor ultrastructure via transmission electron microscopy (TEM) in mouse xenograft models using CAL 27 and CAL 27/ABCB1 cells." (PMID 41189280, 2025). "In this study, we have evaluated the role of ER and RSL3 in sensitizing both ABCB1- and ABCG2-expressing human tumor cells to Adriamycin and Topotecan." (PMID 39859349, 2025). "A pertinent example is the development of valspodar, a small molecule inhibitor targeting ABCB1, which was designed to re-sensitize MDR tumours to chemotherapeutic agents." (PMID 39679367, 2024). "It is suggested that ABC transmembrane transporters (ABCB1, P-gp, MDR1, ABCCs, ABCG2, and MXR) can contribute to the efflux of various drugs from tumor cells." (PMID 38360641, 2024). "In this study, we demonstrate that two ABCB1 substrates, DOX and PTX, induce the increase of labile Zn2+ in tumor cells." (PMID 39507258, 2024). "The subfamily ABCB1/MDR1/P-glycoprotein, ABCC1/MRP1, and ABCG2/BCRP are the most extensively studied and considered as prime factors for the induction of MDR in tumor cells." (PMID 38611964, 2024). "More importantly, treatment with Se-MnP NPs led to down-regulation of MDR-related ABC family proteins (ABCB1 and ABCC1) to reverse MDR in HCT116/DR tumor cells." (PMID 36859296, 2023). "Mechanically, the tumor ECM‐facilitated 5‐FU resistance partly lies in the highly expressed CS chain, which has been demonstrated to promote the expression of ABCB1." (PMID 38020712, 2023). "In a vivo mouse model, SIAH1 knockdown promoted tumor proliferation, increased TC content, and the expression levels of HMGCR and ABCB1, consistent with in vitro results." (PMID 37062828, 2023). "In recent studies, an increase in nitric oxide concentration was shown to mediate drug efflux inhibition by inactivating ATP binding cassette (ABC) transporters, such as ABCB1 (p-gp), ABCC1 (MRP1) and ABCG2 (BCRP) in tumor cells." (PMID 37228164, 2023). "High-grade serous ovarian cancer (HGSOC), one of the most chromosomally unstable tumour types, has a 5-year survival rate of only ~30% — largely due to late diagnosis and rapid development of drug resistance, e.g., via CIN-driven ABCB1 translocations." (PMID 37592171, 2023). "The results showed that the tumor biopsy presented high ABCC6 and ABCC10 expression, and metastasis presented high ABCB1 expression when metastasis was present at diagnosis." (PMID 36982681, 2023). "Both ABCB1 and HIF1A are upregulated under hypoxic conditions, suggesting that HIF1A is related to tumor radiotherapy and chemotherapy resistance mechanisms." (PMID 35659268, 2022). "Reduced SLC2A1, ABCB1, MMP2, twist family bHLH transcription factor 1, and VEGFA expression in tumor cells; downregulation of HIF-1α." (PMID 35640930, 2022). "A011 demonstrated anti-MDR activity by inhibiting the transporting function of ABCB1 and ABCG2 transporters and thus was a potential therapeutic agent for the treatment of tumor resistance." (PMID 36120340, 2022). "However, it has become clear from clinical practice that the basal level of ABCB1 gene expression may not always be a diagnostic sign of tumor resistance." (PMID 35455394, 2022). "ABCB1, BAX, BCL2, FADD, FAS, and several tumour protein families were identified as the genes responsible for such findings." (PMID 35884999, 2022). "P-glycoprotein (Pgp; MDR1; ABCB1) is a plasma membrane ATP-binding cassette (ABC) transporter, responsible for multidrug resistance in tumor cells." (PMID 35563868, 2022). "To examine the resistance of tumour cells to alternative substrates of ABCB1, we combined paclitaxel with TPEN to treat the tumour cells." (PMID 36207295, 2022). "Lapatinib inhibits tumor growth in organoids and cell lines overexpressing HER2 and circumvents ABCB1-mediated chemoresistance after gemcitabine treatment." (PMID 35463361, 2022).
tumor (continued). "c-Myc has been explored as a main transcriptional factor for stemness and ABCB1 expression, while PLK1 is essential for stabilization of c-Myc for tumor survival by phosphorylation-mediated stabilization." (PMID 34503223, 2021). "Most notably, the expression of ABCB1, commonly known as P-glycoprotein (P-gp), and ABCG2, also known as BCRP or the breast cancer resistance protein, in tumor cells has been correlated to poor patients prognosis in numerous studies." (PMID 34993424, 2021). "It is believed that overexpression of ABC efflux proteins (e.g., P-gp/ABCB1, BCRP/ABCG2 and MRP/ABCC1) on the tumor cell membrane is one of the main mechanisms for this clinical resistance." (PMID 33918289, 2021). "Our studies presented here show that NCX4040, a nitric oxide donor derived from aspirin, was significantly cytotoxic to both ABCB1 and ABCG2-expressing human MDR tumor cells." (PMID 33918289, 2021). "The non-treated primary LC samples were collected and grouped based on mutational background; then, qRT-PCR analysis was performed to detect ABCB1 and ABCG2 expression in the resected tumours." (PMID 34065402, 2021). "P-glycoprotein (P-gp, ABCB1) overexpression is, currently, one of the most important multidrug resistance (MDR) mechanisms in tumor cells." (PMID 32555203, 2020). "Second, they regulate drug metabolic pathways by ABCB1- and BCRP-mediated reduction of drug accumulation in tumor cells." (PMID 32284761, 2020). "However, it could induce MDR if ABCB1 transporter gets overexpressed in tumor cells." (PMID 32984343, 2020). "Studies of drug-resistant cell lines derived from human neoplasms identified amplifications of at least 13 ABC transporter genes, including ABCB1, ABCC1 and ABCC4." (PMID 32206879, 2020). "ABCB1 expression was also shown to be maintained at recurrence in cultured cells since EPN7 and EPN7R were derived from primary and recurrent tumours from the same patient." (PMID 31311995, 2019). "In fact, the P-glycoprotein ABCB1 (also known as MDR1, multidrug-resistance protein 1), that is overexpressed in multidrug resistant tumor cell lines, was the first ABC protein identified as such." (PMID 31185645, 2019). "Gemcitabine upregulated the expression level of ABCB1 and ABCG2 in the tumor section when compared with solvent (p < 0.05)." (PMID 31652737, 2019). "The subfamily ABCB1/MDR1/P-glycoprotein, ABCC1/MRP1, and ABCG2/BCRP play a major role in producing MDR in tumor cells." (PMID 31472682, 2019). "Three of the ABC transporters were commonly reported to be responsible for MDR in various tumor types: P-glycoprotein (Pgp, ABCB1), multidrug resistance protein 1 (MRP1, ABCC1), and breast cancer resistance protein (BCRP, ABCG2)." (PMID 29301374, 2018). "The stemness‐associated genes were analysed using RT‐qPCR, and the results showed that the mRNA levels of Nanog, Sox2, Oct4, CD44, CD133, ABCB1, ABCC1, ABCG2 and Notch1 were significantly increased in RCC tumour spheres compared with parental cells." (PMID 30246456, 2018). "In agreement with our in vitro data, PTX treatment induced elevated expression levels of MUC1, ABCB1, and marked increase of EGFR nuclear localization in tumor tissues." (PMID 28796259, 2017). "Overexpression of ABCB1 decreases the intracellular accumulation of chemotherapeutic drugs, and this decrease subsequently induces MDR of the tumor cells to anticancer drugs." (PMID 28881781, 2017). "As a result of comparing tumor cell selectivity, we made a new observation: NTD is transported by the multidrug-resistant transporter Pgp, known as ATP-binding cassette subfamily B member 1 (ABCB1)." (PMID 28529950, 2017). "Recently, we showed that nilotinib reversed ABCB1- and ABCG2-mediated MDR to paclitaxel and DOX, respectively, in nude mouse tumor xenograft models." (PMID 29212189, 2017). "The ABCB1 (P-glycoprotein) inhibitor, nilotinib, was found to alter DOX and DOXol distribution in tumor-bearing mice." (PMID 28283780, 2017).
tumor (continued). "In all tumor samples from CRC patients, abundant ABCB1 protein was present on cell surfaces and cytoplasm of IEC." (PMID 28686677, 2017). "In vivo, we found that the combination of topotecan with the well-tolerated Ko143, a dual inhibitor of ABCB1 and ABCG2, reduced tumor growth by more than 240% compared to single agents treatment, translating to an increase in survival from 17 to 28 days." (PMID 29186899, 2017). "Classical MDR is characterized by upregulation of ABC transporter genes, such as ABCB1 and ABCG2, that transport anticancer agents out of the cell and confer tumor cell resistance to those drugs." (PMID 27050375, 2016). "In contrast, the promoters of ABCB1 and ABCG2 were found to be methylated in ≥ 75% of the tumor tissues." (PMID 27689338, 2016). "Two of these transporters, ABCG2/BCRP and ABCB1/MDR-1, are reported to be the principal sources of the SP phenotype in human tumor cell lines." (PMID 26859746, 2016). "In the tumor tissues analyzed in the present study, the average ABCB1 promoter methylation status ranged from < LOQ to about 50%, whereas in most tumor-adjacent and tumor-distant tissues, the average methylation status was ≤ 10%." (PMID 27689338, 2016). "MED4, MED4R and MED5R demonstrated intermediate ABCB1 expression whereas MED3 cells expressed negligible mRNA and protein, again correlating with protein expression levels in primary tumours." (PMID 24887326, 2014). "ABC transporters specifically, ABCB1, ABCC1 and ABCG2 are expressed not only in tumor tissues but also in normal tissues, such as the liver, kidneys, gastrointestinal tract, and blood-brain barrier." (PMID 25191874, 2014). "In common with the tumour of origin, MED1 cells expressed the highest levels of ABCB1 mRNA and glycosylated ABCB1 protein, thus confirming maintenance of ABCB1 expression in culture." (PMID 24887326, 2014). "In our previous studies, the real-time PCR and Western blotting results showed that ABCB-1/P-gp did drop slightly at the mRNA and protein levels in MCF-7/ADR cells and tumor tissue." (PMID 25372840, 2014). "Expression of multidrug pumps including P-glycoprotein (MDR1, ABCB1) in the plasma membrane of tumor cells often results in decreased intracellular accumulation of anticancer drugs causing serious impediment to successful chemotherapy." (PMID 25309926, 2014). "We analyzed for expression of five ABC transporters ABCB1, ABCC1, ABCC2, ABCC3 and ABCG2 using immunohistochemistry in 103 pre-treatment tumor specimens obtained from patients with CHL." (PMID 22871336, 2012). "Moreover, resistant tumor cells may release membrane microparticles carrying surface ABCB1." (PMID 23259070, 2012). "ABCB1 (P-glycoprotein, P-gp, MDR1), ABCC1-C6 (MRP1-6) and ABCG2 (BCRP) confer resistance to cytostatic drugs of tumors and contribute to the failure of tumor." (PMID 22590507, 2012). "The identified genes are involved in drug transport and detoxification (ABCB1, DNAJC15, GSTP1, RAB6C), DNA damage repair (BRCA1) as well as tumor cell proliferation/invasion (APC, CDH1, ESR1, HIC, PLAU, RASSF1, SULF2, TGM2)." (PMID 20544021, 2010). "Members of the ATP-binding cassette superfamily of proteins (ABCB1 and ABCG2) function to export irinotecan from tumour cells, while drug metabolism via the cytochrome P450 system (CYP3A4) or glucuronidation (UGT1A1) can also occur." (PMID 15655543, 2005). "Further protein analysis via Western blotting revealed that the expression of CAV-1, ABCB1, and ABCC3 proteins in tumor tissues was significantly downregulated in the PPH + PTX group, with the degree of inhibition stronger than that observed in the lovastatin + PTX group." (PMID 41304944, 2025). "For this reason, we correlated the mRNA expression of ABCB1 in 58 NCI tumor cell lines not preselected for drug resistance with the log10IC50 expression for our set of 30 anthracycline derivatives." (PMID 40723843, 2025).
tumor (continued). "Collectively, these data demonstrated that KSQ‐4279 could widely and significantly potentiate the chemotherapeutic cytotoxicity of traditional agents in the ABCB1‐, ABCG2‐, and ABCC1‐induced MDR tumor cells in vitro." (PMID 41328326, 2025). "Mechanistically, POLR2J4 knockdown reduced the expression of drug resistance genes (ABCB1, ABCC1, BCL2), decreased serum levels of IL-6 and TGF-β1, and downregulated TGF-β1 and PD-L1 in tumor tissues, highlighting its role in establishing an immunosuppressive, drug-resistant microenvironment." (PMID 40661083, 2025). "Given our previous findings that melatonin induces tumor cell apoptosis through excessive ROS production, we addressed whether it also induces ROS in HNSCC/ABCB1 cells." (PMID 41189280, 2025). "Furthermore, efflux pumps (ABCB1, MRP1) and influx transporters (SLC7A11) significantly impact drug bioavailability, while age-dependent CYP metabolism and tumor-specific isoforms such as CYP2W1 represent metabolic vulnerabilities." (PMID 41425252, 2025). "Silencing ABCB1 or AKR1C3, or overexpressing LDHB, suppressed KIRC cell proliferation and migration in vitro; LDHB overexpression combined with sorafenib significantly reduced tumor growth in vivo." (PMID 40977852, 2025). "Moreover, there was a significant decrease in the tumour volume in mice as well as a significant reduction in the expression of HER2, ABCB1 and BCL2 markers in both in vitro and in vivo samples." (PMID 40867257, 2025). "The ABCB1 and ABCG2 drug efflux transporters can also be expressed in tumor cells themselves." (PMID 40893689, 2025). "We also found that inflammatory changes in tumor tissues during anticancer therapy, such as increased IL-8 production, induce MDR1/ABCB1 expression in TECs, resulting in resistance to paclitaxel, which is mediated by ABCB1." (PMID 38318528, 2024). "What is most important is that these compounds only slightly influenced the expression of the ABCB1, ABCC1, and ABCC2 genes and the level of the MDR1 protein in the studied colon LS 174T and prostate DU 145 tumor cells, especially for the C-2028, C-2045, and C-2053 derivatives." (PMID 39683740, 2024). "Furthermore, the mRNA expression levels of ABCC3 (p = 0.020) and ABCB1, also known as p-glycoprotein (p = 0.008), exhibited a significant downregulation in the tumour tissues of COS patients tumour when compared to the healthy donors." (PMID 39335211, 2024). "Some studies have indicated that the ABCB1 TT genotype is connected with poor tumor response, while meta-analyses have failed to confirm a substantial link between ABCB1 variations and chemotherapy response." (PMID 39598531, 2024). "Furthermore, ABCB1-p-glycoprotein (p = 0.008) and ABCC3 (p = 0.020) exhibited a significant downregulation in the COS tumour tissues when compared to the healthy donors." (PMID 39335211, 2024). "The results revealed increased ABCB1 and CYP1B1 expression in tumor samples of the poor responders." (PMID 38534761, 2024). "For example, ABCB1 is located on the cell membrane and uses ATP hydrolysis to transport various compounds, including chemotherapeutic agents, out of cells, leading to MDR in tumor cells." (PMID 39852431, 2024). "The ABCB1 protein, also known as MDR-1 (multidrug resistance) protein or P-glycoprotein (P-GP), is an ATP-dependent membrane transporter responsible for multiple chemotherapy agents’ efflux and prevention of their accumulation within the tumor cell." (PMID 37569269, 2023). "Furthermore, according to these 7 key genes (ABCB1, CAP1, EGFR, ITGB1, MAPK1, PPARG, SNCA), we plotted the KM curves to show the survival state of high and low expression groups in tumor samples from the TCGA-PAAD dataset." (PMID 37857015, 2023). "Finally, in vivo studies further demonstrated that Se-MnP and OX@Se-MnP NPs reversed MDR in tumor cells and induced tumor apoptosis to suppress tumor growth by down-regulating the expression of MDR-related ABC transporters proteins (ABCB1, ABCC1 and ABCG2)." (PMID 36859296, 2023).